RNU6-490P (RNA, U6 small nuclear 490, pseudogene)
Gene: Small nuclear RNA gene on chromosome 10 (27,088,321 to 27,088,427, reverse strand). Ensembl gene ENSG00000199855.
Homologues: Orthologues: chimpanzee U6 (99% identical). Paralogues in human: RNU6-1011P (88% identical), RNU6-38P (88% identical), RNU6-480P (88% identical), RNU6-12P (87% identical), RNU6-13P (87% identical), RNU6-32P (87% identical), RNU6-33P (87% identical), RNU6-7 (87% identical), RNU6-774P (87% identical), RNU6-8 (87% identical), RNU6-1 (86% identical), RNU6-1005P (86% identical), and 1285 more.